CDH7 (cadherin 7)
Description:
Cadherins are calcium-dependent cell adhesion proteins. They preferentially interact with themselves in a homophilic manner in connecting cells; cadherins may thus contribute to the sorting of heterogeneous cell types.
Synonyms: CDH7L1
Tractability: Antibody: its Gene Ontology location is reachable by antibodies, with high confidence; UniProt places it where antibodies can reach, with medium confidence; UniProt predicts a signal peptide or a membrane-spanning region.
Gene: Protein-coding gene on chromosome 18 (65,750,252 to 65,890,337, forward strand). Ensembl gene ENSG00000081138.
Subcellular location: Cell membrane
Pathways (Reactome):
Cell-Cell communication: Adherens junctions interactions
Gene Ontology:
Molecular function: beta-catenin binding; cadherin binding; calcium ion binding
Biological process: adherens junction organization; calcium-dependent cell-cell adhesion; cell migration; cell morphogenesis; cell-cell adhesion; cell-cell adhesion mediated by cadherin; cell-cell junction assembly; cell adhesion; homophilic cell-cell adhesion
Cellular component: adherens junction; catenin complex; plasma membrane; membrane
Genetic constraint (gnomAD): Loss-of-function variants: 24 observed, 61.18 expected, observed/expected ratio (o/e) 0.39, 90% interval 0.28 to 0.55. The upper end of that interval is the gene's LOEUF score, 0.55, which puts it in group 2 of 6, group 1 being the genes least tolerant of losing a copy. Missense variants: 758 observed, 886.99 expected, observed/expected ratio (o/e) 0.85, 90% interval 0.8 to 0.91. Synonymous variants: 336 observed, 337.64 expected, observed/expected ratio (o/e) 1, 90% interval 0.91 to 1.09.
Homologues: Orthologues: chimpanzee CDH7 (100% identical), macaque CDH7 (99% identical), dog CDH7 (99% identical), pig CDH7 (99% identical), mouse Cdh7 (98% identical), rat Cdh7 (96% identical), rabbit CDH7 (96% identical), tropical clawed frog cdh7 (84% identical), zebrafish cdh7a (73% identical), guinea pig CDH7 (73% identical), zebrafish cdh7b (45% identical). Paralogues in human: CDH20 (61% identical), CDH18 (60% identical), CDH10 (60% identical), CDH6 (59% identical), CDH8 (59% identical), CDH9 (58% identical), CDH11 (57% identical), CDH12 (57% identical), CDH22 (55% identical), CDH19 (50% identical), CDH24 (49% identical), CDH5 (39% identical), and 21 more.
Diseases named in the same sentence as CDH7 in open-access papers:
CDH7 is named in the same sentence as 29 diseases in open-access papers, as found by Europe PMC text mining. Sharing a sentence is not in itself a finding about the gene and the disease. The quoted sentences say what the papers report.
schizophrenia (5 papers, 2016 to 2024). A major psychotic disorder characterized by abnormalities in the perception or expression of reality. "CDH7 and CDH12 have been associated with bipolar disorders and CDH18 was found to be associated with schizophrenia." (PMID 39570883, 2024). "Moreover, a group of cadherins, CDH7, CDH12, CDH18 and PCDH12, are reported to be associated with bipolar disease and schizophrenia." (PMID 30148849, 2018). "Schizophrenia genes relevant to cell adhesion comprised of several members of the cadherin family CDH22, CDH4, CDH7 and CDH9 as well as the protocadherin PCDH10." (PMID 34859219, 2021).
CHARGE syndrome (4 papers, 2017 to 2022). CHARGE syndrome is a multiple congenital anomaly syndrome characterized by the variable combination of multiple anomalies, mainly Coloboma; Choanal atresia/stenosis; Cranial nerve dysfunction; Characteristic ear anomalies (known as the major 4 C's). "In the case of CHARGE syndrome (n = 4), only one subject carried a detectable CDH7 variant; likewise, in the case of Waardenburg syndrome (n = 2), only one subject carried a detectable PAX3 variant." (PMID 35853923, 2022). "CHARGE syndrome with chromodomain-helicase-DNA-binding protein 7 (CDH7) gene mutation is a genetic disease with an autosomal dominant gene." (PMID 33391964, 2020). "Remarkably, some patients with a CDH15 deletion share specific clinical traits with CHARGE syndrome, associated with heterozygous CDH7 variants." (PMID 28422132, 2017).
malignant melanoma (4 papers, 2011 to 2021). "CDH7 is a typical adhesion molecule, and some studies have shown that CDH7 is a melanoma inhibitory protein binding partner that affects the migration of malignant melanoma cells." (PMID 32010623, 2019). "It was shown that CDH7 plays a role in tumor development of malignant melanoma cells by interacting with melanoma inhibitory activity protein (MIA) and migration melanoma cell." (PMID 25077705, 2014). "MIA/cadherin-7 interactions were shown to regulate cell-cell adhesion of malignant melanoma cells, influencing their migration." (PMID 21726432, 2011).
bipolar disorder (3 papers, 2017 to 2024). A disorder of the brain that causes unusual shifts in mood, energy, activity levels and the ability to carry out day-to-day tasks. "Interestingly, genome-wide association studies in humans demonstrated that common variants in Cdh7 were associated with bipolar disorder and major depressive disorder (MDD), indicating the comorbidity of MDD and alcohol." (PMID 28000031, 2017).
breast carcinoma (3 papers, 2017 to 2025). "Another seven genes (CDH13, CDH7, CTNNA2, ERBB4, GRIK1, PCDH15, and TCF7L2) were reported as associated with the breast cancer by recent GWA studies." (PMID 28615668, 2017).
major depressive disorder (3 papers, 2016 to 2021). An episode of depression lasting two or more weeks without an intervening episode of mania. "The best two-point linkage within the region was found at 18q22.1 near CDH7 and CDH19 genes (LOD 3.3), and the best joint LD and linkage was found at rs11152166 (p-value 5.1*10−5, dominant model), which has previously been linked to major depressive disorder." (PMID 26909693, 2016).
gastric cancer (2 papers, 2022). A primary or metastatic malignant neoplasm involving the stomach. "By analyzing gastric cancer (GC) patients in two independent cohorts, Luo and co-workers showed that cadherins CDH2, CDH6, CDH7 and CDH10 were significantly associated with a poor GC prognosis." (PMID 35631574, 2022).
colon cancer (1 paper, 2023).
Di George syndrome (1 paper, 2023). "Di George syndrome and CHARGE were suspected and the patient underwent peripheral venous blood karyotype examination with FISH study of the 22q11.2 region, and CDH7 analysis was executed." (PMID 36672860, 2023).
pancreatic NET (1 paper, 2023). "In addition, a CDH7::BEND2 fusion has been found in a case report of a hepatic metastasis of a pancreatic NET G3, but there was no mention of ectopic ACTH secretion by the tumor." (PMID 36690805, 2023).
tumor (7 papers, 2013 to 2025). "Methylation appeared to be dysregulated in CPM with a bias towards a hypermethylator phenotype caused by somatic mutation of the TET2 tumour suppressor and CDH7 chromatin regulator." (PMID 33144643, 2020). "Both CFD and CDH7 expression levels were observed to be downregulated in the tumour group." (PMID 40429821, 2025). "Similarly, CDH7 plays a crucial role in cell–cell interactions, tissue formation, and migration, and its expression is downregulated in tumours." (PMID 40429821, 2025). "By analyzing the relationship between the prognostic CDH genes and the abundance of tumor immune infiltration, we found that expression level of CDH6 (r = 0.138, P = 7.82 × 10−3) and CDH7 (r = 0.104, P = 4.57 × 10−2) were significantly related to B cell infiltration in GC tumor tissues." (PMID 34880371, 2021). "Mutation analyses of genes in the 18q22.1 region including CDH7 and CDH19 did not reveal any tumor specific mutations, suggesting that other mechanisms of gene inactivation are operational." (PMID 24165089, 2013). "This region encompasses the CDH19 and CDH7 genes, however, we could not confirm the loss of CDH19 in tumor 16 with the small deletion in 18q22.1." (PMID 24165089, 2013).
infection (2 papers, 2013 to 2024). The state of being infected such as from the introduction of a foreign agent such as serum, vaccine, antigenic substance or organism. "It is worth noting, there were also several poorly characterized infection-promoting plasma membrane protein targets, like CDH7, which may contribute to viral entry." (PMID 39772154, 2024).
CDH7 also shares sentences with these, for which no sentence is quoted: cancer (2 papers); colorectal cancer (2); colorectal tumor (2); alopecia (1); autism spectrum disorder (1); cerebral small vessel disease (1); depression (1); developmental delay (1); genetic disease (1); hyperhomocysteinemia (1); psychiatric disorder (1); Sepsis (1); Tinnitus (1); tobacco use disorder (1); trichotillomania (1); triple-negative breast carcinoma (1); Waardenburg syndrome (1).